YTHDF2 (YTH N6-methyladenosine RNA binding protein F2)
Diseases named in the same sentence as YTHDF2 in open-access papers (continued):
Sharing a sentence is not in itself a finding about the gene and the disease.
cancer (197 papers, 2018 to 2026). A tumor composed of atypical neoplastic, often pleomorphic cells that invade other tissues. "To study the clinical significance of the YTHDF2-regulated epitranscriptome in human cancers, we examined the association of YTHDF2-regulated targets with patient prognosis." (PMID 36973285, 2023). "YTHDF2 is closely associated with cancer progression, however, little is known about the function of YTHDF2 in GC." (PMID 36870954, 2023). "Then, we mapped the mutation data of 15 different cancers from TCGA to further analyze the specific types of YTHDF2 mutation." (PMID 36120577, 2022). "In summary, we tried to provide a comprehensive bioinformatics analysis on the expression, mutation and promoter methylation of YTHDF2 across cancers, and investigated its predictive value on prognosis." (PMID 36120577, 2022). "Here, the associated mechanisms of YTHDF2 in human cancers are listed and separated by its different expression patterns in various tumors." (PMID 35382893, 2022). "High expression of YTHDF1 and METTL3 has been reported to be associated with lower OS in cancer patients, and YTHDF2, YTHDF1 and METTL3 were proved to be associated with sorafenib treatment and anti-PD-1 immunotherapy response in HCC." (PMID 36618420, 2022). "Accumulating evidence suggests that YTHDF2 is greatly implicated in many aspects of human cancers and non-cancers through various mechanisms." (PMID 33593354, 2021). "Herein, we focus on concluding YTHDF2-associated mechanisms and potential biological functions in kinds of cancers and non-cancers, and its prospects as a prognostic biomarker." (PMID 33593354, 2021). "Based on current researches, it was found that the expression of YTHDF2 was closely associated with cancer prognosis." (PMID 33593354, 2021). "Herein, we concluded the biological functions and the role of YTHDF2 in diverse diseases, especially cancers, and hoped to reveal the underlying mechanisms." (PMID 33593354, 2021). "We examined the functional status of YTHDF2 across various cancer types in the CancerSEA database to better understand the relevance and underlying mechanisms of YTHDF2 expression in cancer." (PMID 34512342, 2021). "For example, the m6A levels were increased through miR-145 targeting YTHDF2, which caused the suppression of cancer cell proliferation in HCC." (PMID 35003212, 2021). "Through genetic remodeling and m6A-mRNA profiling, we link YTHDF2 deficiency to mRNA stabilization of IL-11 and Serpin E2, the key mediators in support of hypoxia-induced cancer cell survival and vascular reconstruction." (PMID 31735169, 2019). "Administration of a first-in-class HIF-2α antagonist (PT2385) restored and required YTHDF2 to suppress inflammation-associated cancer progression." (PMID 31735169, 2019). "YTHDF2 dysregulation was often associated with cancer, but it has also been found that the locus corresponding to the (TG)n microsatellite in the YTHDF2 gene could play a potential role in human longevity." (PMID 39619978, 2024). "The high mutation potential, CNVs and methylation of YTHDF2 in cancers might all contribute to the development and progression of various tumors." (PMID 36120577, 2022). "Therefore, further investigations are still needed to clarify the discrepancies to obtain better identifications of the effects and the underlying mechanisms of YTHDF2 in different cancers." (PMID 35382893, 2022). "Further researches might focus on the upstream molecular regulation mechanisms to explore the causes of YTHDF2 disorders in human cancers." (PMID 33593354, 2021). "For YTHDF2 gene SNPs and cancer risk, only one study has been conducted." (PMID 34539889, 2021). "The affected genes (MAP2K4 and YTHDF2) have both been implicated in cancer development." (PMID 34158539, 2021).
cancer (continued). "Comprehensive analysis suggested that the differences in YTHDF2 expression and prognostic values in different types of cancer may reflect underlying mechanisms associated with different biological characteristics." (PMID 32986017, 2020). "YTHDF2 was shown to be associated with some cancer patient prognosis." (PMID 33505426, 2020). "Thus, HIF-2α-mediated inhibition of YTHDF2 in HCC promotes cancer-associated inflammation." (PMID 37369946, 2023). "The analyses showed that YTHDF2 expression and associated prognoses may depend on cancer type." (PMID 32986017, 2020). "This is likely because the overexpression of YTHDF2 decreased the mRNA stability of KDM6B in cancer cells." (PMID 39800682, 2025). "This indicated that YTHDF2 was responsible for m6A induced degradation of GATA3 mRNA in cancer cells." (PMID 39800682, 2025). "YTHDF2 exhibits a complex and context-dependent role in cancer biology, with its function varying across different types of research." (PMID 40675967, 2025). "Understanding these nuances is crucial for formulating targeted strategies that can exploit the differential effects of YTHDF2 in cancer treatment." (PMID 40675967, 2025). "In prostate cancer, YTHDF2 expression was increased in cancer tissues compared with adjacent normal tissues." (PMID 40356909, 2025). "YTHDF2, as the first m6A reading protein to be discovered, has generally been demonstrated to play an oncogene role in a variety of cancers." (PMID 40356909, 2025). "For example, FTO-mediated m6A modification of lncRNA LINC00022 improves its stability and stimulates cancer cell proliferation by recognizing YTHDF2." (PMID 39904996, 2025). "YTHDF2 drives the cancer stem cell phenotype and metastatic progression in Liver cancer by augmenting octamer-binding transcription factor 4 (OCT4) expression via m6A methylation." (PMID 40986143, 2025). "YTHDF2 knockdown results in significant reductions in the migration and invasion abilities of cancer cells." (PMID 40986143, 2025). "The m6A modification levels of HAR1A were increased in cancer cells, while YTHDF2 was responsible for recognizing m6A modification in the HAR1A, leading to the disintegration of this lncRNA." (PMID 38688909, 2024). "YTHDF2 can have different effects on cancer therapy resistance depending on the type and context of the cancer." (PMID 38351531, 2024). "Several RNA-binding proteins, including LIN28, Musashi, and YTHDF2, have been reported to regulate cancer progression." (PMID 39420119, 2024). "Accumulating evidence has demonstrated that the ubiquitination of RNA reader proteins, such as IGF2BPs and YTHDF2, significantly affects cancer progression." (PMID 39377984, 2024). "YTHDF2 has an essential regulatory role in various cancers,472, 473, 474 and acts as either an oncogene or tumor suppressor gene in different cancers depending on context." (PMID 39006762, 2024). "Another study revealed that YTHDF2 promoted cancer metastasis and increased cancer stemness by influencing OCT4 expression via m6A RNA methylation in liver cancer." (PMID 39199296, 2024). "The RNA-binding protein YTH N6-methyladenosine RNA-binding protein F2 (YTHDF2) contributes to cancer progression by incompletely understood mechanisms." (PMID 38776708, 2024). "For instance, YTHDF2 acts as a cancer-promoting regulator in certain tumors, such as glioblastoma, acute myeloid leukemia and prostate cancer." (PMID 39054967, 2024). "YTHDF2 can also be SUMOylated at site K571, thereby enhancing its binding affinity with m6A-modified mRNAs and accelerating cancer advancement." (PMID 36999016, 2023). "Up to now, LncRNA FENDRR, LncRNA FGF14-AS2, LncRNA THOR, LncRNA-CBSLR, and LncRNA STEAP3-AS1, have been evidenced to interplay with YTHDF2, thus regulating the proliferation, metastasis, invasion and ferroptosis of various cancer cells." (PMID 37365581, 2023).
cancer (continued). "In cancer, histone methylation upregulates the expression of METTL3, which mediates m6A, and YTHDF2, which recognizes m6A, thereby promoting cancer progression." (PMID 36774341, 2023). "In summary, YTHDF2, for the most part, modulates the degradation of mRNAs containing m6A modification, but it also exerts m6A-independent regulation in cancer development." (PMID 36870954, 2023). "Of YTH domain-containing proteins in cancer, YTHDF2 is the firstly identified reader protein and the most extensively studied." (PMID 37598390, 2023). "YTHDF2 promotes the degradation of mRNA and cancer progression by increasing its binding affinity to m6A‐modified mRNAs." (PMID 37366340, 2023). "In particular, YTHDF2 can regulate cancer progression by binding to m6A-modified sites to mediate mRNA degradation." (PMID 37156816, 2023). "YTH domain-containing family protein 2 (YTHDF2) recognizes m6A-cotaining RNAs and accelerates degradation to regulate cancer progression." (PMID 37012388, 2023). "YTHDF2 has been reported to have indispensable effect on various physiological courses, for example, neural development, cancer progression, and hematopoietic stem cell expansion." (PMID 36277978, 2022). "Based on the controversial role of YTHDF2 in various cancers, we summarized its expression patterns and molecular mechanisms in tumorigenesis and discussed the potential prognostic and therapeutic value of YTHDF2 in malignant tumors." (PMID 35382893, 2022). "Silencing of YTHDF2 led to an increase in circ_SFMBT2 expression while inhibiting the malignancy of cancer cells." (PMID 35924072, 2022). "A recent study demonstrated that the m6A reader YTHDF2 specifically stabilizes MYC mRNA in cancer stem cells and that YTHDF2 provides a therapeutic target to interfere with MYC signaling in GBM." (PMID 35265626, 2022). "More importantly, the underlying molecular mechanism and the clinical prognostic and therapeutic value of YTHDF2 in several cancers were also discussed." (PMID 35382893, 2022). "Sumoylation of YTHDF2 can increase its ability to bind to m6A-modified mRNA to downregulate target gene expression, ultimately inducing cancer." (PMID 36578520, 2022). "As a result, YTHDF2 was positively correlated with MMR gene expression in all the cancer types, excluding CHOL and UCS." (PMID 36120577, 2022). "In this way, the finding in this current study further validates the cooperation of METTL14 and YTHDF2 in affecting human cancers." (PMID 36288387, 2022). "The expression pattern of YTHDF2 has been confirmed in numerous studies, and the expression level of YTHDF2 has been found to vary in different types of cancer." (PMID 35382893, 2022). "ACC, UCEC, and SKCM-P are the top three cancers with significant correlation between YTHDF2 expression and immune scores." (PMID 36120577, 2022). "A series of survival-associated analyses including OS, DSS, and PFI were conducted to evaluate the predictive potential of YTHDF2 for prognosis across cancers." (PMID 36120577, 2022). "As the prognostic role of YTHDF2 has been discovered in the pan-cancer research, it is meaningful to explore the relationship between YTHDF2 expression and immune infiltration." (PMID 36120577, 2022). "TGCT, ACC and UCEC are the top three cancers with significant correlation between YTHDF2 expression and stromal scores." (PMID 36120577, 2022). "In the present study, we performed a pan-cancer analysis and tried to investigate the expression of YTHDF2 and its predictive value on prognosis across various tumors." (PMID 36120577, 2022). "As TMB has been proven to be an immune-response biomarker that can effectively predict the immunotherapeutic effects of immune checkpoint blockers (ICBs), we examined the association between YTHDF2 expression and TMB in different cancers." (PMID 36120577, 2022).
cancer (continued). "Our study found that YTHDF2 expression was positively correlated with MMR genes in all cancers excluding CHOL and UCS." (PMID 36120577, 2022). "YTH domain-containing family protein 1 (YTHDF1) or YTHDF2 play crucial roles in cancer immunotherapy." (PMID 36479088, 2022). "Accumulating evidence demonstrated that YTHDF2, as a member of m6A reader protein, plays a crucial role in RNA metabolism and cancers progression." (PMID 35661004, 2022). "The overexpression of FTO facilitated cancer progression by stabilizing heat shock transcription factor 1 (HSF1) in a YTHDF2-dependent way." (PMID 34804925, 2021). "YTHDF2 advanced the cancer stem cell (CSC) liver phenotype and HCC lung metastases by adjusting the m6A methylation in the 5′UTR of OCT4 mRNA." (PMID 33593354, 2021). "YTHDF2 was found to promote the liver cancer stem cell phenotype and cancer metastasis by enhancing OCT4 mRNA translation in a m6A-dependent manner." (PMID 33928028, 2021). "YTHDF2 is responsible for maintaining the dynamic N6-methyladenosine (m6A) modification balance and influences a variety of cancers." (PMID 34539889, 2021). "Growing evidence has been added to support the critical role of YTHDF2 in the regulation of cancer cell proliferation and migration." (PMID 34539889, 2021). "In general, YTHDF2 was highly expressed in most human cancers from TCGA pan-cancer database; whereas, its mRNA expression in KICH, KIRP, PCPG, THCA, and THYM was notably lower than that in adjacent normal tissue." (PMID 33980824, 2021). "Overexpressed PVT1 can suppress the binding of YTHDF2 with PVT1 to promote cancer cell proliferation." (PMID 35004679, 2021). "In patientswith high-risk cancer, ZC3H13 expression is upregulated, while the expression of METTL3, KIAA1429, YTHDF1 and YTHDF2 is downregulated." (PMID 34246319, 2021). "Accumulating evidence showed that YTHDF2, as a member of m6A “readers”, played a significant role in multiple diseases, such as hematopathy and cancers." (PMID 33593354, 2021). "Regarding other types of cancer, YTHDF2 is overexpressed in acute myeloid leukemia and is required for disease initiation." (PMID 33795663, 2021). "The expression of YTHDF2 in cancer tissues was also up-regulated (p < 0.05), while those of RRP8, YTHDC1, and YTHDF3 were not significantly different." (PMID 34195072, 2021). "To validate this interaction, we performed the reciprocal co-IP assays and indeed verified that FBW7 binds to YTHDF2 in SKOV3 cancer cells." (PMID 33658012, 2021). "Another important reader, YTHDF2, is also well researched and has been found to be closely related to human cancer." (PMID 33795663, 2021). "Many studies have demonstrated the involvement of YTHDF2 in the regulation of m6A modified targets in cancer development." (PMID 34970571, 2021). "An interactive bubble map was used to investigate the expression of YTHDF2 and the behavior of each functional state using single-cell datasets for various cancers." (PMID 34512342, 2021). "METTL3 as the core writer, it’s frequently reported to mediate RNA metabolism cooperating with the downstream directly-executive reader YTHDF2 in various diseases especially in cancers." (PMID 33121495, 2020). "Initially, we used an online tool (TIMER) to investigate YTHDF2 expression in different cancer types." (PMID 33344502, 2020). "Using various publicly available databases, we investigated YTHDF2 expression and its relationship with the prognosis of cancer patients." (PMID 33344502, 2020). "In this study, we analyzed YTHDF2 expression and its correlation with the prognosis of cancer patients via a pan-cancer analysis using various web-based platforms." (PMID 32986017, 2020). "In summary, our data provide a comprehensive bioinformatics analysis of YTHDF2 expression and prognostic value in human cancers." (PMID 32986017, 2020). "In the present study, we first performed a pan-cancer analysis to analyze YTHDF2 expression and prognostic value." (PMID 32986017, 2020).
cancer (continued). "We then used the ONCOMINE database to compare YTHDF2 expression in human cancer and corresponding normal samples." (PMID 32986017, 2020). "We explored the role of YTHDF2 in LIHC based on publicly available datasets [The Cancer Genome Atlas (TCGA), International Cancer Genome Consortium (ICGC), and Gene Expression Omnibus (GEO)]." (PMID 33344502, 2020). "In multiple cancer types, YTHDF2 expression in cancer tissues was significantly higher than that in adjacent normal tissues." (PMID 33344502, 2020). "ZC3H13 was upregulated in patients with high cancer risk, whereas METTL3, KIAA1429, YTHDF1, and YTHDF2 were downregulated." (PMID 32631107, 2020). "YTHDF2 is a well know m6A reader and plays an important role in the progression of several cancers via regulating mRNA degradation." (PMID 32814762, 2020). "YTHDF2 expression substantially impacted the prognosis of four cancer types, including brain, breast, colorectal, and soft tissue." (PMID 32986017, 2020). "RT-qPCR detected that the mRNA expression of YTHDF2 was increased (p < 0.05), while miR-495 expression was reduced in patient cancer tissues (p < 0.05)." (PMID 33087165, 2020). "In contrast, another m6A-modified mRNA reader protein YTHDF2, which recognizes m6A and reduces the stability of its targeted transcripts, is mostly deleted in human cancers." (PMID 31653849, 2019). "Together, our data highlight a protective role of YTHDF2 in HCC interrupting the hypoxia-induced epigenetic-inflammation-cancer axis." (PMID 31735169, 2019). "In contrast, overexpression of YTHDF2 not only arrested cancer cell growth but also reduced vessel density and permeability." (PMID 31735169, 2019). "This study specified the suppressive potential of YTHDF2 in cancer-promoting inflammation, and established a context of metabolic-epigenetic regulation where hypoxia imposes a cancer-specific procedure of m6A-mRNA editing." (PMID 31735169, 2019). "Our results have characterized the m6A-mRNA landscape in human HCC and revealed YTHDF2 as a molecular ‘rheostat’ in epitranscriptome and cancer progression." (PMID 31735169, 2019). "In accordance, HIF-2α blockade improves YTHDF2-mediated suppression on m6A-mRNA stability and inflammatory cancer behaviors, leveraging this metabolic-epigenetic axis toward therapeutic opportunities in human HCC." (PMID 31735169, 2019). "To find out the key determinants in a hypoxic cancer context, we used a combined screening approach by integrating YTHDF2-regulated transcriptional profiling and the hypoxia-responsive epitranscriptome." (PMID 31735169, 2019). "Previously, the role of m6A modification in cancers were rarely studied, especially with regard to YTHDF2, its specific functions and mechanisms in PCa still remained elusive." (PMID 29423080, 2018). "Notably, genes including CAV1, ITGB1, BNIP3, and YTHDF2 were associated with the AKT signalling pathway, suggesting a functional link between ODC1 activity and cancer progression." (PMID 41803527, 2026). "Remarkably, the concurrent inhibition of m6A readers YTHDF1 and YTHDF2 in combination with ICIs may mitigate resistance to immunotherapy in cancer." (PMID 39987091, 2025). "Furthermore, YTHDF2 is widely studied in a review, which mentioned the YTHDF2 implication in various aspects of human cancers through different mechanisms." (PMID 38075202, 2024). "Importantly, YTHDF2 ubiquitination mediated by ubiquitin ligases or non‐coding RNAs is critical in regulating cancer development." (PMID 39377984, 2024). "The discrepancy in the regulation of the different processes of an oncogenic mRNA raised the possibility that the dual effects of YTHDF2 (as a promoter of mRNA degradation and a facilitator of translation) in cancers are exerted via its regulation of the different processes related to mRNA biology." (PMID 38247171, 2024). "The expression profiling of YTHDF2 has been found to differ in different types of cancer." (PMID 36870954, 2023).